NPM1 (nucleophosmin 1)
Diseases named in the same sentence as NPM1 in open-access papers (continued):
Sharing a sentence is not in itself a finding about the gene and the disease.
cancer (continued). "Whether this is also true in human ALK-driven cancer remains to be elucidated, although our initial analysis with ALK-F1174L and the NPM1::ALK fusion oncogenes that are known oncogenic variants in human cancer would suggest that this may be the case." (PMID 32917927, 2020). "Thus, we predicted that increased expression of NPM1 in cancer cells is involved in suppression of p27 function." (PMID 33050036, 2020). "Moreover, NPM1 silencing and p27 induction in cancer cells significantly suppressed their proliferation in mouse xenografts." (PMID 33050036, 2020). "Many other molecules targeting NPM1 have also been developed for cancer treatment." (PMID 31462227, 2019). "Previous studies showed that NPM1 is downregulated in cancer cells during drug-induced apoptosis." (PMID 29963261, 2018). "Instead, overexpression of the NPM1 gene is frequently observed in different solid tumors, e.g., ovarian, prostate, colon, bladder, thyroid, lung and liver cancers." (PMID 30126426, 2018). "NPM1 is frequently overexpressed in cancer and is mainly located in the nucleus." (PMID 29535419, 2018). "With the ratio of 92.8% upregulation and 7.2% downregulation, we can infer that ‘NPM1’ may act as an upregulated protein in cancer progression." (PMID 29688359, 2018). "These included Eno1, LDHB, NPM1, PKM2 and KPNA2, which are commonly overexpressed in NSCLC, are associated with poor prognosis, and are therefore potentially relevant targets for cancer immunotherapy." (PMID 29258618, 2017). "NPM1 also plays important roles in cancer since it is over-expressed in proliferating cells compared to normal cells and has been proposed to be a marker of different solid tumors such as prostate, colon, ovarian, gastric, bladder, hepatomic, oral and thyroid carcinomas." (PMID 26993766, 2016). "The specific contribution of overexpressed NPM1 to cancer development is not fully understood but it may arise from multiple factors." (PMID 27058426, 2016). "Since NPM1 is overexpressed in many types of cancer and because of its role in genome stability, it could be a potential target for new cancer therapy strategies." (PMID 27553022, 2016). "This suggests that interfering with NPM1 status or functions may be a general way to sensitize cancer cells." (PMID 27058426, 2016). "From a cancer perspective, elevated levels of NPM1 might promote malignant transformation by enabling cell survival." (PMID 27553022, 2016). "Lastly, we shall look at how NPM1 dysfunction contributes to cancer pathologies." (PMID 27553022, 2016). "The different locations of NPM1 in cancer cells may indicate a different role of NPM1 in the tumorigenesis pathway." (PMID 25779011, 2015). "Conversely, when NPM1 is overexpressed, such as in cancer cells, histones could be removed from DNA, leading to an open chromatin conformation." (PMID 25711412, 2015). "Efforts to pharmacologically target NPM1 for cancer therapy might be difficult, due to the fact that its function is likely to be tightly regulated to avoid the possibly detrimental consequences of its decreased or increased function." (PMID 24410879, 2014). "NPM1 could then be a target to switch off specifically ERK1/2 pathway activation in order to decrease or inhibit cancer cell growth and migration." (PMID 24796332, 2014). "The NPM1 protein is frequently overexpressed in solid tumours of diverse histological origin, and it has been regarded as a marker for gastric, colon, ovarian and prostate carcinomas." (PMID 25663821, 2014). "Although much evidence demonstrates that NPM1 expression correlates with clinical parameters of cancer patients, the detailed role of NPM1 in cancer progression is largely unknown." (PMID 22631075, 2012). "Among 13 cases of cancer tissues with distant metastasis, 12 showed positive staining for NPM1." (PMID 22631075, 2012).
cancer (continued). "The current study speculated that NPM1 may play a role in the elevated invasive potential of cancer cells and investigated the effect of NPM1 knockdown on cancer cell migration and invasion using a Boyden chamber assay." (PMID 22631075, 2012). "Increased levels of NPM1 may at least in part reflect a higher growth rate and an increased demand for ribosome biogenesis in cancer cells and NPM1 is induced when B-cells, T-cells and Swiss 3T3 cells are stimulated with various mitotic agents." (PMID 21152184, 2011). "Modulation of RNA pol I transcription could be a critical activity of NPM1 because changes in rDNA transcription is an important molecular alteration in cancer cells." (PMID 21152184, 2011). "Under the assumption that high levels of NPM1 makes cancer cells addicted to it, knocking down NPM1 using RNAi or small molecule inhibitors could block cell growth." (PMID 21152184, 2011). "In addition, snoRA51 enhanced cancer stem cell-like properties via the RPL3/NPM1/c-MYC pathway." (PMID 41510246, 2025). "Therefore, our research indicated that the NAT10/NPM1 axis could be a promising target for cancer treatment." (PMID 38243170, 2024). "Besides, several recent studies have suggested NPM1 as a good target for targeted cancer therapy." (PMID 38467827, 2024). "Moreover, this expression may influence specific downstream targets such as Rearranged L-myc fusion (RLF) and Nucleophosmin 1 (NPM1) expression—critical mediators of cancer growth and chemotherapy resistance." (PMID 36674758, 2023). "Even though down‐regulation of KPNA2 could significantly repress cancer cell proliferation and further invasion ability, we found that overexpression of NPM1 could promote cell proliferation, as well as the migration ability and invasion of cancer cells in some degree." (PMID 34469024, 2021). "Interestingly, high NPM1 expression is associated with negative prognostic outcome in the combined cohort of patients with these 11 cancer types and with higher risk in seven of them when analyzed individually." (PMID 34388291, 2021). "In addition, a Boolean model derived from a smaller network-module representing the crosstalk between FLT3, DNMT3A, NPM1 and cancer hallmarks, when primed with patient-specific genomic profiles, yielded predictions that are in accord with patients’ clinical data." (PMID 33578936, 2021). "Taking all these data into account, we identified the following candidates as potential causes of CA in human cancer: gain of function of CEP19, CEP72, CTNNB1, PTK2, NDRG1, SPATC1, TBCCD1; and loss of function of CEP76, MCPH1, NEURL4, NPM1." (PMID 32681070, 2020). "Second, because the S34F cells require NPM1 for their viability, we hypothesized that the S34F mutation should not co-occur in cancer patients with NPM1 loss of function mutations." (PMID 33137094, 2020). "NPM1 is not the only ALK fusion partner that has been associated with cancer." (PMID 31366041, 2019). "Furthermore, FOXM1 may be a potential therapeutic target in ALK + ALCL, and disruption of the binding between FOXM1 and NPM1 in the NPM-ALK—NPM1 heterodimers may serve as a highly specific anti-cancer therapeutic approach for NPM-ALK + ALCL." (PMID 31390744, 2019). "Moreover, we investigated whether targeting APE1 endonuclease activity or its interaction with NPM1 may sensitize TNBC cancer cells to Pt-compounds treatment." (PMID 31307523, 2019). "We suggest that this region of NPM1 may be targeted for cancer treatment." (PMID 28920929, 2017). "Interestingly, disruption of the β-hairpin “latch” in wild-type NPM1 with NSC348884 led to increased apoptosis in various cancer cell lines, suggesting that post-translational modifications in this area may have important functional consequences." (PMID 25490769, 2014). "In addition, NPM1 is reported to be overexpressed in solid tumors of diverse histological origins, including astrocytomas, as well as colon, hepatocellular, bladder, breast, ovarian and prostate carcinomas." (PMID 25663821, 2014).
cancer (continued). "Interestingly, similar results were also observed in other solid tumors, indicating that NPM1 may be a potential prognosis marker for cancer patients." (PMID 22631075, 2012). "The current study hypothesized that NPM1 may play a role in cancer cell migration and invasion." (PMID 22631075, 2012). "In summary, loss of one allele of NPM1 is one step closer to cancer but it is also worth noting that NPM1 has not been shown to repress genes involved in cell cycle progression, induce apoptosis in response to cell damage, or to induce cell cycle arrest following DNA damage." (PMID 21152184, 2011). "Similarly, in a Cancer and Leukemia Group B study, which included 196 adult AML patients from two clinical studies, WT1 mutation predicted a worse 3-year disease-free and OS compared to wild-type WT1 AML patients independently of CEBPA, FLT3-ITD, and NPM1 mutational status." (PMID 41102401, 2026). "To assess if this link between NPM1 and WNT/MYC signaling was detectable in human cancer, we first examined human tumors from The Cancer Genome Atlas (TCGA)." (PMID 41413654, 2026). "Revumenib and a second KMT2A-Menin inhibitor, ziftomenib, have also shown efficacy in the treatment of other cancers dependent on KMT2A function, such as NPM1-mutant leukemias." (PMID 41279818, 2025). "ICAM-1 participates in cell migration and proliferation via NFκB, NPM1, Pho/JNK, GTP/LFA-1/JAK/STAT3, and Ras/RAF/MEK/ERK activates the Raf/MEK/ERK pathway which is responsible for cancer cell proliferation and migration." (PMID 39149564, 2024). "Accordingly, we detected a strong correlation between NPM1 and MYC expression, which has also been reported for other cancers before." (PMID 39529166, 2024). "In specific cases, the depletion of nucleolar proteins such as nucleophosmin 1 (NPM1) in human and mouse normal fibroblasts and cancer cells has been shown to result in rearrangements of perinucleolar heterochromatin." (PMID 38279227, 2024). "Our findings underscore NAT10’s oncogenic role in promoting glycolysis-immunosuppression crosstalk within cancer cells and show that NAT10-induced NPM1 acetylation enhances PD-L1 transcription and expression, strengthening immune evasion." (PMID 39648231, 2024). "The control of the HIF‐1α/NPM1 interaction by ERK‐dependent phosphorylation of HIF‐1α extends the role played by the ERK pathway both in normal and cancer cells." (PMID 34388291, 2021). "This led to the identification of NPM1 as a direct binding partner of HIF‐1α both in vitro and inside cancer cells." (PMID 34388291, 2021). "Specifically, being upregulated in multiple types of cancer, LETN resides in the nucleolus via direct binding with NPM1." (PMID 33432115, 2021). "This category also includes many known biomarkers for cancer diagnosis or targeted treatment, such as APC Q1291* (for COAD), EGFR L858R (for LUAD), BRAF V600E (for THCA and SKCM), DNMT3A R882H and NPM1 W288Cfs*12 (for LAML)." (PMID 31925297, 2020). "Ultimately, similar to what is seen with targeted therapies in multiple cancers, a resistance caused by clonal heterogeneity or escape could emerge; therefore, safe combination strategies will be key for achieving cures for all AML patients with a mutated NPM1 gene." (PMID 32545659, 2020). "In some cancers, mutant forms of NPM1 including the one fused to ALK, anaplastic lymphoma receptor tyrosine kinase, and NPM1c+ (NPM1 cytoplasmic positive) are known." (PMID 33050036, 2020). "APE1 and NPM1 protect cancer cells from Pt-compounds cytotoxicity, suggesting a possible improvement of the activity of Pt-based therapy for TNBC, using the NPM1 and APE1 proteins as second therapeutic targets." (PMID 31307523, 2019). "Bioinformatics analysis, using TCGA datasets, was performed to predict a molecular signature of cancers based on APE1 and NPM1 expression." (PMID 31307523, 2019).
cancer (continued). "This mis-localization hampers canonical functions of NPM1 and affects APE1 nuclear BER function in cancer cells, through relocalization of APE1 itself in the cytoplasm." (PMID 31307523, 2019). "Specific missense mutation matches have been found to six proteins from the COSMIC Cancer Gene Census database (FLNA, RPL22, SDHA, NFATC2, NPM1, and CLTCL1)." (PMID 31316139, 2019). "Therefore, NPM1 might represent a potential target for cancer therapy." (PMID 30357352, 2018). "Overall, though very preliminary, these data suggest that a molecule targeting the NPM1 surface that interacts with HIV Rev, plays a toxic effect on cancer cells." (PMID 27058426, 2016). "Another peptide is CIGB-300 (P15-TAT), an anticancer peptide that can bind NPM1 and prevent CK2 driven phosphorylation leading to nucleolar breakdown and cancer cell apoptosis." (PMID 21152184, 2011). "It was shown that NPM1 inhibition leads to apoptosis and sensitizes NPM1c+‐expressing AML cells to drugs such as ATRA and cytarabine, suggesting that NPM1 is a target for cancer therapy." (PMID 41114465, 2026). "In addition, we showed that selinexor, a selective inhibitor of XPO1 that has been used as a pan-cancer agent in preclinical and phase I clinical trials, effectively inhibits the growth of AML cells harboring the NPM1-fusions, as it does in NPM1c AML." (PMID 39443736, 2024). "Both NPM1 and TGFB2 have been shown to promote cancer cell growth and metastasis, we thus determined whether snoVector‐expressed oncoproteins exert these oncogenic activities." (PMID 37063610, 2023). "Rearrangements in the organization of the nucleoli structure have been previously observed in fibroblasts and cancer cells as well as in oocytes lacking NPM1 or its isoforms (Holmberg Olausson, Nistér and Lindström, 2014)." (PMID 37759327, 2023). "The NPM1 may adversely affect ESCA cells’ cuproptosis process by altering copper ion levels, which ultimately affects cancer development." (PMID 36188614, 2022). "It is possible that NPM1 may be able to influence the methylation level of ESCA by affecting m6A, and ultimately affect the development of cancer." (PMID 36188614, 2022). "Therefore, based on the results of our study, we propose that NPM1–LETN plays a critical role in ensuring the hyperactive nucleolar state, to which cancer is known to be ‘addicted’ for rapid growth." (PMID 33432115, 2021). "LGALS1, NPM1, RACK1, and PERP were upregulated from ductal to cancer cells." (PMID 34326696, 2021). "Based on previous studies, SAMD12‐AS1 was considered to promote cell proliferation through the interaction with NPM1, while abnormal regulation of BLACAT1 could also promote the proliferation and metastasis of cancer cells." (PMID 33934391, 2021). "Interestingly, alterations in JAK2, MYD88 and NPM1 genes, already have drugs FDA approved for other cancers." (PMID 33668731, 2021). "Together, our research has revealed NPM1 as a transcription regulator of PD-L1 in TNBC, which could lead to potential therapeutic strategies to enhance the efficacy of cancer immunotherapy." (PMID 32245950, 2020). "An anti-cancer agent, YTR107, was also shown to act by binding to NPM1 and altering its function." (PMID 27553022, 2016). "We hypothesize that the NPM1 dependent positive regulation of cancer cell migration and invasion secondary to ERK1/2 activation may result from recruitment of K-Ras to the membrane by NPM1." (PMID 24796332, 2014). "Inhibition of NPM1 in cancer cells but not in normal cells is therefore an attractive, but still theoretical, therapeutic approach." (PMID 21152184, 2011).
cancer (continued). "Second, different proteoforms from the same cancer-related gene (e.g., DAP, CALM1, HDGF, JPT1, RALY, and NPM1) may have potentially varied biological functions in modulating CRC metastasis, because they show opposite expression profiles between the SW480 and SW620 cells." (PMID 36542699, 2022). "Nonetheless, the immune regulation activity of NPM1 in cancer has not been reported." (PMID 32245950, 2020). "NPM1 function is regulated primarily through phosphorylation by PLK1, that leads to the protection from cell death; Indeed, the inhibitor of PLK1, that induces apoptosis, is used in the treatment of several cancers, including esophageal cancer, neuroblastomas, and others." (PMID 27326393, 2016). "However, low levels of NPM1 have also been observed in some cancers, such as gastric cancers (mRNA and protein) compared to normal tissue." (PMID 27553022, 2016). "Furthermore, the NPM1 level in cancer tissues and paired noncancerous tissues of 12 patients was tested, and the results revealed that NPM1 expression was significantly increased in cancer tissues." (PMID 37875480, 2023). "Therefore, NPM1 may be a target for TNBC treatment and potentially other cancer types as well." (PMID 32245950, 2020). "This indicates that PCa cells are dependent on NPM1 and FBL for cancer progression than noncancerous cells." (PMID 40705480, 2025). "Moreover, in order to confirm that the secretion of APE1 is common in vesicles from non-cancer cell lines, we used two mouse embryonic fibroblast (MEF) cell lines expressing or not Nucleophosmin 1 (NPM1), a known APE1–protein interacting partner." (PMID 33753167, 2021).